CXCL5 (C-X-C motif chemokine ligand 5)
Diseases named in the same sentence as CXCL5 in open-access papers (continued):
Sharing a sentence is not in itself a finding about the gene and the disease.
tumor (continued). "Chemokines (CXCL12, CXCL8, CXCL5) and chemokine receptors (CXCR1/2, CCR4, CCR8) are well-known to deeply participate in the tumor development and progression in various cancers, including LUAD." (PMID 36419650, 2022). "Tumor cells additionally facilitate the development of MDSCs by secreting CCL2, CCL12, CXCL5 to attract IMCs into the TME while also secreting growth factors that recruit MDSCs in the bone marrow." (PMID 35345849, 2022). "On the other hand, myeloid derived suppressor cells are recruited by CCL-2, CXCL-5, CXCL-8 and CXCL-12 into the TME, building a tumor-promoting and immune-suppressive microenvironment." (PMID 36611932, 2022). "In CRC, a number of studies have confirmed that some molecules, such as MyD88, SREBP1, and CXCL5, promoted CRC cell proliferation, migration, invasion, and tumor growth through NF-κB activation." (PMID 35309901, 2022). "CAFs can additionally increase the expression of PD-L1 on tumor cell surfaces by expressing CXCL5, which engages CXCR2 on tumor cells and upregulates PD-L1 by activating PI3K/AKT signaling." (PMID 35345849, 2022). "In recent years, the CXCL5/CXCR2 axis has received increasing attention for its potential in cancer screening, tumor prognosis and personalized anticancer therapy." (PMID 35702353, 2022). "Solid tumors produce chemokines like CXCL1, CXCL12, and CXCL5 within the TME, preventing T cells from reaching the tumor cells." (PMID 35844304, 2022). "CXCR2 binds chemokines containing the glutamic acid-leucine-arginine (ELR) motif such as CXCL5 and CXCL8 that are involved in angiogenesis and also promote tumor progression." (PMID 34831316, 2021). "CXCL5 can also activate protein kinase B (PKB) and activator of transcription (STAT) signaling pathways and promote tumor angiogenesis." (PMID 33869023, 2021). "It has been shown that certain tumours produce chemotactic agents, such as TNFα; IL‐17; CXCR2 ligands CXCL1, CXCL2, CXCL5, and CXCL6, to attract neutrophils." (PMID 33665979, 2021). "MDSC was reported to participant in tumor metastatic in a pre-metastatic niche pattern, in which MDSC can attract tumor cells via CXCL5/CXCR2 interaction." (PMID 34689842, 2021). "It is well known that tumor cells or stromal cells in the tumor microenvironment secrete chemokines such as C-C motif chemokine ligand 2 (CCL2), C-X-C motif chemokine ligand 1 (CXCL1), CXCL2, and CXCL5." (PMID 34209505, 2021). "This was explained by the fact that CD14high tumor cells have a higher production of IL6, IL8/CXCL5, CXCL1, CXCL2, M-CSF, VEGF-A, FGF-2 than CD14low tumor cells." (PMID 34572939, 2021). "In response to OV therapy, neutrophils can accumulate in the tumour, destroying the tumour vasculature and inducing apoptosis through secretion of reactive oxygen species, cytokines and proteases, including CXCL1 and CXCL5." (PMID 34888493, 2021). "In another study, the number of PMN-MDSCs in the tumor tissue of 48 RCC patients correlated with IL-8 and CXCL5 expression." (PMID 34445235, 2021). "Scoring from 82 tumor samples identified a positive correlation between DDR1 expression and CXCL5 production (Pearson’s r = 0.4460; 95% CI, 0.2535–0.6045) and Ly6G+ TAN infiltration (r = 0.2840; 95% CI, 0.07144–0.4720)." (PMID 34237033, 2021). "Another study demonstrated that CXCL5 has the greatest fold increase in human PDAC and correlated with both tumor-infiltrating CD15+ granulocytes and neutrophil elastase+ (NE+) granulocytes." (PMID 34439836, 2021). "On the contrary, several sets of chemokines and their receptors, such as CCR2/CCL2, CXCR2/CXCL5, and VEGF, have been reported to promote tumor progression in other tumors by enhancing immunosuppressive M2-TAM and MDSC function." (PMID 34200100, 2021).
tumor (continued). "The chemokine receptor CXCR2 and its ligands CXCL1, CXCL2, CXCL3, CXCL5 and CXCL8 play critical roles in the chemoattraction of neutrophils towards tumor tissues." (PMID 34429454, 2021). "Chemokine C-X-C motif ligand 5 (CXCL5) belongs to the CXC family, which can bind to the G protein coupled receptor CXCR2, thereby affecting tumor growth, proliferation and metastasis." (PMID 33640021, 2021). "The differential expression of the CXCL5 gene is the key to the prognosis of HCC; therefore, CXCL5 can be used to evaluate tumor progression, block tumor progression, and predict tumor prognosis." (PMID 33955820, 2021). "On the other hand, CAFs promote the expression of PD-L1 in tumor cells by secreting CXCL2 and CXCL5, and macrophages upregulate PD-L1 expression through TGF-β–induced EMT, which plays a critical role in tumor immunosuppression and immune evasion." (PMID 34395525, 2021). "For example, N-myc downstream regulated gene 1 (NDRG1)/Cap43 downregulates the expression of CXCL1, CXCL5, CXCL8, and VEGF in tumor cells, leading to the suppression of neutrophil infiltration." (PMID 34439836, 2021). "Lung epithelial cells, when exposed to tumor-derived exosomal RNAs, are also able to recruit neutrophils by secreting CXCL1, CXCL2, CXCL5, and CXCL1214." (PMID 34707103, 2021). "Both liver tumor tissue, as well as tumor draining LN, showed a significantly increased expression of CXCR2 and CXCL5 compared to the normal liver and naïve LNs from the control animals." (PMID 34831316, 2021). "CXCL5 recruits neutrophils into the TME, and the CXCL5/CXCR2 axis contributes to tumor growth and metastasis through the activation of PI3K/AKT/GSK-3β/Snail signaling to promote EMT." (PMID 34237033, 2021). "In hormone-independent prostate cancer, CXCL5 (also known as ENA78) enhances EGR1 transcription via the RAF–MEK–ERK pathway, thus increasing SNAIL expression, tumor cell metastasis, and EMT." (PMID 33842351, 2021). "The M-MDSC is attracted to tumor sites by CCL2, CCL5, and CSF1 and PMN-MDSC was attracted by CXCL1, CXCL5, CXCL6, CXCL8, and CXCL12." (PMID 34858479, 2021). "This is consistent with our findings that CXCL5, a CXCR2 ligand, is expressed by tumor cells in a DDR1-dependent manner and drives neutrophil activation and NET formation." (PMID 34237033, 2021). "CXCR2 promotes the process of metastasogenesis and tumor growth, while the two chemokines that bind to CXCR2 (CXCL1 and CXCL5) are released by macrophages, and this process is supported by GC cells." (PMID 33182840, 2020). "In this setting, G-CSF operates in partnership with tumor-derived neutrophil chemoattractants, most prominently the chemokines CXCL5 (also known as epithelial neutrophil-activating peptide-78; ENA-78) and CXCL8 (IL-8)." (PMID 33233675, 2020). "We included both anti- and pro-inflammatory cytokines involved in tumor suppression such as TNF-α, IL-1β, and tumor promotion such as IL-10, CCL22, CXCL5, and TGF-β (selection of cytokines based on ref.)." (PMID 33267818, 2020). "Epithelial-derived neutrophil-activating peptide-78 (ENA78/CXCL5) is upregulated in many cancers and involved in tumor progression." (PMID 32632106, 2020). "Higher CXCL5 protein abundance was observed in seven PDAC tumor tissues and six cell lines compared to adjacent non-tumor tissues or normal pancreatic ductal epithelial cell line HPDE6-C7." (PMID 32201508, 2020).
tumor (continued). "We found that reactive CAFs induce resistance to FSS to tumor cells by forming a protective cellular nodule and by soluble factors such as: CCL2, CCL7 and CXCL5." (PMID 32256977, 2020). "CXCL5, ELN, JUN, and FGFR4 were highly expressed in normal tissues, while PLAU, RNASE7, JAG1, SPP1, and TNFRSF18 were highly expressed in tumor tissues." (PMID 32699529, 2020). "CXCL5 exerts these effects by activating ERK/Snail signaling pathway in GC cells and inducing pro-tumor activation of neutrophils." (PMID 32632106, 2020). "Since several types of MDSCs express CXCR2, intratumor production of CXCL5 and CXCL8 is important to migration of MDSCs in the tumor microenvironment." (PMID 32707850, 2020). "In order to determine the mechanism of neutrophils recruitment into the tumour, we screened neutrophil attracting chemokines (CXCL1, CXCL2, CXCL3, CXCL5, CXCL8 and CXCL12)." (PMID 32778818, 2020). "The M1 phenotype has anti-inflammatory and anti-tumor effects and secretes proinflammatory factors such as interleukin-1 (IL-1), IL-12, IL-23, TNF-α, chemokine (C-X-C motif) ligand 5 (CXCL5), CXCL9, and CXCL10." (PMID 32296030, 2020). "IL-4 is generated by both tumor cells and stromal cells, and IL-4 neutralization resulted in reduced levels of the chemokines CCL2, CCL11, and CXCL5 in the TME." (PMID 33178603, 2020). "Measurements of 36 different chemokines in the culture medium revealed a significant decrease in the secretion of CCL5, CCL8, CXCL1, CXCL2, CXCL5, and TGFβ1 and a significant increase in TGFβ2 secretion by TB9-Fhit transfected tumor cells." (PMID 32545680, 2020). "IL-17 not only enhances tumor-infiltrating MDSCs, probably by increasing CXCL1 and CXCL5 secretion by tumor cells, but also potentiates their inhibition on T cells through upregulation of ARG1 and IDO." (PMID 32793192, 2020). "Fifteen days after inoculation, intraperitoneal injection of CXCL5 antibody, GM-CSF antibody or iNOS antagonist 1400 W dramatically reduced the accumulation of PMN-MDSCs in the bone marrow, lungs and primary tumour sites compared with IgG-negative control." (PMID 31819035, 2019). "In particular, the CXCR2-ligands CXCL5 and CXCL2 contribute to neutrophil accumulation and inhibit T-cell-dependent suppression of tumor growth." (PMID 31561620, 2019). "The expression of CXCL1, CXCL2, CXCL5, and CXCL8, which are CXCR2 ligands, and the expression of KITL and GM-CSF are strongly enhanced by KRAS signaling in cancer cells and tumor-derived hypoxia." (PMID 31474975, 2019). "Intraperitoneal injection of bexarotene significantly decreased expressions of CCL22, CXCL5, CXCL10, and p19 in the tumor microenvironment." (PMID 31616630, 2019). "In our previous study, we demonstrated that CXCL5 was upregulated in CRC and was able to promote tumor metastasis through induction of EMT in CRC tumor cells." (PMID 30792394, 2019). "On the other hand, CXCL5, and CXCL7 platelet secretion in distant sites to the primary tumor recruit granulocytes to prepare the pre-metastatic niche." (PMID 31417569, 2019). "CXCL5 over-expression in human HCC samples does well correlate with high neutrophil content, shorter OS, and tumor recurrence." (PMID 31799175, 2019). "Platelets have a role in managing the pre-metastatic communications; they secrete CXCL5 and CXCL7 upon contact with tumor cells to recruit granulocytes for the formation of the early metastatic niche." (PMID 31417569, 2019). "The expression levels of five genes (ADAM28, BTBD6, CXCL5, PCDH1, and LOC102724689) comprise three rules for the identification of pancreatic-tissue-derived PDX tumor tissues." (PMID 31456818, 2019). "Treatment with CXCL5 antibody, the iNOS inhibitor 1400w and GM-CSF antibody reduced MDSC expansion in the bone marrow, primary tumour sites and metastatic sites, and promoted the efficiency of PD-L1 antibody." (PMID 31819035, 2019).
tumor (continued). "Intraperitoneal administration of bexarotene significantly decreased expressions of CCL22, CXCL5, CXCL10, IL-4, and p19 mRNA in the tumor microenvironment." (PMID 31616630, 2019). "The chemokines CXCL1, CXCL2, CXCL5, CXCL6, and CXCL8 secreted from tumor cells attract neutrophils in the blood to the tumor microenvironment via CXCR1 and CXCR2 on the surface of neutrophils." (PMID 30736371, 2019). "The Snail-expressing cancer cells secrete increased levels of CXCL5 and CXCL2 to recruit more pro-tumoral neutrophils to the tumor, creating a positive amplifying loop to facilitate tumor growth." (PMID 31474975, 2019). "For example, we have previously shown that the local tumour microenvironment of mCRC patients contains high levels of the chemokines CXCL1, CXCL5, and CCL2 which have proangiogenic properties." (PMID 29535825, 2018). "Within the tumor microenvironment, platelets secrete CXCL5 and CXCL7, as a consequence of direct contact with tumor cells or following activation of the coagulation cascade, thus supporting the recruitment of CXCR2-positive myeloid cells." (PMID 30591657, 2018). "Secondly, discharge of CXCL5 and CXCL7 from platelet granules has been shown to be controlled by direct binding between platelets and tumor cells as well as the plasmatic coagulation cascade." (PMID 29346400, 2018). "Neutrophils are recruited at the tumor sites by several chemokine signals, such as CXCL12, CXCL8, CCL3 (MIP-1α), and CXCL6 (huGCP-2), or murine chemokines CXCL1, CXCL2, and CXCL5." (PMID 30591657, 2018). "Nonetheless, with the present study, we reveal how heparin affects the release of VEGF and chemokines CXCL5 and CXCL7 in the early metastatic spread of tumor cells." (PMID 29346400, 2018). "CXCL5 can bind CXCR2 to mediate various cellular behaviours that include neutrophil recruitment and tumour cell migration and invasion." (PMID 29665837, 2018). "It is notable that MDSCs infiltrating primary tumor lesions by sensing CXCL1, CXCL2, and CXCL5 promote epithelial-mesenchymal transition (EMT) and dissemination of cancer cells, by secreting TGF-β, EGF, and HGF." (PMID 30591657, 2018). "The concomitant expression of CXCL5 and CXCR2 makes a substantial contribution to the tumour progression of NPCs." (PMID 29665837, 2018). "For instance, the chemokines CXCL5 and CXCL7, derived from platelets, have been proven to recruit granulocytes to tumor cells circulating in the blood." (PMID 29346400, 2018). "In contrast, the release of platelet-derived chemokines CXCL5 and CXCL7 depends on both, a thrombin-mediated platelet activation and a direct interaction between tumor cells and platelets." (PMID 29346400, 2018). "Recently, the platelet-derived chemokines CXCL5 and CXCL7 were revealed to recruit granulocytes to circulating tumor cells contributing to tumor cell survival, extravasation and finally formation of metastatic foci." (PMID 29346400, 2018). "In addition, pre-treatment of lung cell preparations with anti-CXCL5 neutralizing antibody or blockade of its receptor CXCR2 on ESCC cells abrogated the enhanced invasion of ESCC cells attracted by the lung preparations from mice bearing Id1-expressing tumours." (PMID 28186102, 2017). "We detected a concentration gradient for the CXCR2 ligands CXCL1, CXCL2, CXCL5, CXCL6 and CXCL8 between the plasma and the tumor tissues of patients with primary RCC." (PMID 28923105, 2017). "CXCL1, CXCL5 and CXCL8 were overall the most abundant chemokines present in the RCC tumor supernatants." (PMID 28923105, 2017). "TAN secretes several cytokines and chemokines such as CXCL5, TGFβ, and TNF during tumor development and metastasis." (PMID 29379802, 2017). "Among these differentially expressed genes, pro-inflammatory cytokines, such as IL6, CXCL1, CXCL5, CXCL8, and CSF2 were further validated as significantly downregulated in WCE-treated PC-3 and DU145 tumor tissues." (PMID 29142311, 2017).
tumor (continued). "Among these, CXCL1, CXCL5, and CXCL8 have been described to stimulate PCa cell proliferation, cell survival, migration, invasion, and angiogenesis, thus promoting tumor growth as well as metastasis." (PMID 29142311, 2017). "Thus, TME at primary site increases tumor dispersion via paracrine signals by generating a chemotactic relay system, a case that can be further exemplified by CXCL14 secreted by CAFs, or EGF and CXCL5 released by tumor-associated dendritic cells in prostate and lung tumors, respectively." (PMID 25857315, 2015). "Tumor-derived CXCR2-ligands, CXCL1, CXCL2, and CXCL5, have been known to promote recruitment of MDSCs to the site of tumor or to the premetastatic niche." (PMID 26078490, 2015). "Together, we provided an evidence that CXCL5 was a critical chemokine for DACH1-mediated repression of motility and tumor growth." (PMID 25788272, 2015). "Tumor-derived CXCR2-ligands (IL-8, CXCL1, CXCL2, and CXCL5) attract MDSCs to the tumor microenvironment and inhibition of CXCR2 profoundly suppresses Gr-1+ leukocyte migration into tumor." (PMID 26078490, 2015). "A direct correlation between CXCL5 tissue levels in surgical specimens of NSCLC and the extent of capillary density consistent with tumor angiogenesis has been reported." (PMID 24971349, 2014). "It is further evidenced by recent studies that CXCL5 was over-expressed in HCC patients with shorter overall survival and high tumor recurrence." (PMID 25011526, 2014). "The aberrations of three selected genes, CXCL5, DLX5 and RUNX2, were validated in five cell lines and five tumour samples using PCR techniques." (PMID 23144859, 2012). "Chemokines such as CXCL1 and CXCL8 are able to enhance tumor cell proliferation; CXCL5 and CXCL12 attract neutrophils and MDSC, while CXCL12 promotes the migration of tumor cells that express the cognate receptor CXCR4." (PMID 22927846, 2012). "CXCL5, a member of the CXC chemokine family, has been shown to be involved in angiogenesis, tumor growth, and metastasis." (PMID 22950635, 2012). "Since CXCL5 is the most highly expressed of the three CXCR2 ligands, it is the prime candidate for mediating the preferential attraction of PMN-MDSC to the tumor." (PMID 21980263, 2011). "The TCM components CCL2, CXCL1, CXCL5 and VEGF seem to play a role in modulating the inflammatory response through inhibition of IL-12p70 secretion by DCs, possibly to protect the tumour from a potent immunologic response against it." (PMID 22125641, 2011). "Several cytokines and chemokines are present at high levels in the tumour microenvironment, compared to normal tissues, such as CCL2 (MCP-1), CXCL1 (GROα) and CXCL5 (ENA-78)." (PMID 22125641, 2011). "Transcriptome analysis of purified tumor-infiltrating immune cells indicated that only PMN-MDSC express Il8rb (also known as CXCR2), the receptor for CXCL1, CXCL2, and CXCL5." (PMID 21980263, 2011). "While the effect of CXCL1 and CXCL5 on DC maturation and cytokine secretion has not been previously investigated, their known function is to attract and activate neutrophils, which in turn have been implicated with tumour cell growth, angiogenesis and metastasis." (PMID 22125641, 2011). "CFD/Adipsin median levels were found to be lower in tumours compared to the levels in PN and AN (p = 0.0324), while CXCL5/ENA78, CCL20/MIP-3α, IGFBP3, SPP1/OPN and TIMP1 were increased in PN and tumours relative to AN, with higher levels seen in tumours." (PMID 21092330, 2010). "These authors demonstrated that a deficiency in the receptor resulted in an increase in CXCL5 (ENA-78) and SDF-1α in the tumor microenvironment." (PMID 20490273, 2010). "Several cytokine mRNAs' (CCL3/MIP-1α, CCL15/MIP-1δ, CXCL1, CXCL5/ENA78, CXCL8/IL8, CXCL9/MIG, CXCL10/IP10) were found to be overexpressed in the tumours while CCL15/MIP-1δ, CXCL5/ENA78 and IL8 mRNAs' were overexpressed in paired normals, as well." (PMID 21092330, 2010).